DMP1 (dentin matrix acidic phosphoprotein 1)
Diseases named in the same sentence as DMP1 in open-access papers (continued):
Sharing a sentence is not in itself a finding about the gene and the disease.
rickets (24 papers, 2010 to 2025). Bone softening and weakening usually caused by deficiency or impaired metabolism of vitamin D. Deficiency of calcium, magnesium, or phosphorus may also cause rickets. "Mutations in DMP1 have been associated with diseases such as osteomalacia and rickets due to altered phosphate metabolism." (PMID 36683528, 2023). "Deficiency in active 1,25-dihydroxyvitamin D (1,25(OH)2D) often associated with rickets can affect the vitamin D receptor-mediated expression of mineralization inhibitors such as DMP1." (PMID 26347868, 2015). "Deletion of Dmp1 in mice or mutations in DMP1 in humans causes hypophosphatemic rickets with an elevated circulating level of FGF23, which is responsible for the impaired renal tubular reabsorption of phosphate." (PMID 22879941, 2012). "Taken together, our results strongly suggest that the R145X substitution is causative for inherited rickets in Corriedale sheep, disrupting the function of the DMP1 protein, preventing successful bone mineralization and phosphate homeostasis." (PMID 21747952, 2011). "Corriedale sheep with the mutation in DMP1 also developed rickets, were severely hypophosphataemic and had normal serum 1,25(OH)2D3 concentrations." (PMID 21747952, 2011). "Mutation on DMP1 gene could cause abnormalities in bone development, such as osteomalcia and rickets." (PMID 31304101, 2019). "Our studies also showed improvement of the rickets/osteomalacia phenotype, and dramatically enhanced bone modeling in the compound deficient mice, suggesting that the low phosphate level plays a key pathological role in Dmp1−/− mice." (PMID 22879941, 2012). "We also attempted to test whether elevation of blood Pi levels due to Klotho deficiency would rescue the rickets phenotype in Dmp1−/− mice." (PMID 22879941, 2012). "Treatment with phosphate supplementation and active vitamin D was shown to improve rickets and normalize serum ALP levels in patients with ARHR1 which is due to mutations in the dentin matrix protein 1 (DMP1) gene." (PMID 35352187, 2022). "A similar approach also helped identify the dentin matrix protein 1 gene (DMP1) as responsible for inherited rickets in Corriedale sheep and the solute carrier family 13 (sodium/sulphate symporters), member 1 (SLC13A1) gene for chondrodysplasia in Texel sheep." (PMID 23762451, 2013). "Here we used Dmp1 null mice, a hypophosphatemic rickets/osteomalacia model, combined with a metatarsal organ culture and an application of neutralizing fibroblast growth factor 23 (FGF-23) antibodies to gain insight into the roles of Pi in bone biology." (PMID 21542006, 2011). "Interestingly, Dmp1−/−kl/kl mice show a dramatic improvement of rickets and an identical serum biochemical phenotype to kl/kl mice (extremely high FGF23, hyperphosphatemia and reduced parathyroid hormone (PTH) levels)." (PMID 22879941, 2012). "Affected sheep could be used as animal models for this form of human rickets, and for further investigation of the role of DMP1 in phosphate homeostasis." (PMID 21747952, 2011). "One gene called DMP1 in the largest 125-SNP region was considered the most plausible candidate due to its biological functions involved in mineralization and phosphate homeostasis and previous reports of its involvement in human rickets." (PMID 21747952, 2011). "Dmp1−/− mice, like hyp mice (a well-studied hypophosphatemic rickets animal model), display abnormally high FGF23, low serum Pi, rickets and osteomalacia, which is a consequence of the defects in the osteocytes." (PMID 22879941, 2012). "Taken together, the reduction of DMP1 and elevation of OPN in the matrix of bone may be aggravating factors in the development of rickets in FAM20C-defcient subjects." (PMID 28620244, 2017). "As shown in a recent report that a lack of DMP-1 gave rise to rickets or osteomalacia in mice, a possible role of osteocytes mediating DMP-1 appears to be the local regulation of mineralization." (PMID 22547998, 2012).
rickets (continued). "Sanger sequencing and multiplex ligand-dependent probe amplification analysis of PHEX and Sanger sequencing of FGF23, DMP1, ENPP1KL, and FAM20C were performed to assess genotype in patients with HH with or without rickets in all pediatric hospital departments across Norway." (PMID 26543054, 2016).
osteomalacia (22 papers, 2010 to 2025). Disorder caused by an interruption of the mineralization of organic bone matrix leading to bone softening, bone pain, and weakness. "Osteocytes also express PHEX, DMP1, ENPP1, and FAM20C, and inactivating mutations cause FGF23-related hypophosphatemic rickets/osteomalacia." (PMID 36246908, 2022). "Further, the constitutive expression of β-catenin in osteocytes recaptures a similar osteomalacia phenotype as shown in Dmp1 null or Hyp mice." (PMID 34326685, 2021). "The von Kossa stain, a common staining protocol used for detection of mineralization defects, showed a complete rescue of the osteomalacia in Dmp1 null mice by the full-length Dmp1 transgene." (PMID 20734454, 2011). "These mutant mice displayed an osteomalacia phenotype identical to that of Dmp1-KO mice." (PMID 34326685, 2021). "Similar osteocyte alterations were reported in DMP1−/− mice with osteomalacia, suggesting that bone mineralization and osteocyte morphology defects observed in mice with advanced CKD may be caused, in part, by reduced DMP1 expression." (PMID 31044094, 2019). "Interestingly, increased E11 protein was observed in osteocytes from the DMP1-null mouse, which is characterized by diffuse osteomalacia and reduced mineral density." (PMID 22586496, 2012). "Interestingly, we noticed that in the long bone, the restoration of phosphate homeostasis by FGF-23 antibodies only partially rescued the bone-formation rate and osteomalacia, suggesting that DMP1 also plays a direct role in mineralization." (PMID 21542006, 2011). "However, serial analysis of gene expression identified DMP1 and PHEX as overexpressed genes in tumors responsible for tumor-induced osteomalacia and secreting FGF23." (PMID 36776964, 2023).
hypophosphatemic rickets (21 papers, 2011 to 2025). Rickets due to low serum phosphate concentrations, the cause of which can be nutritional or genetic. "One autosomal recessive hypophosphatemic rickets family carried a mutation affecting the dentin matrix protein (DMP1) start codon." (PMID 32733380, 2020). "Autosomal-recessive forms of hypophosphatemic rickets (ARHR) may be caused by mutations in dentin matrix protein 1 (DMP1, as in ARHR1) or ectonucleotide pyrophosphatase/phosphodiesterase 1 (ENPP1, as in ARHR2)." (PMID 33815294, 2021). "PHEX or DMP1 mutations cause hypophosphatemic-rickets and altered energy metabolism." (PMID 24839967, 2014). "This protein is involved in calcification in bone, and when DMP1 is suppressed, fibroblast growth factor 23 (FGF23) is highly expressed in bone cells; FGF23 in the blood can increase, causing autosomal recessive hypophosphatemic rickets." (PMID 41040543, 2025). "It was reported that CRISPR/Cas9-mediated ablation of DMP1 in rabbit caused the phenotype similar to human ARHR1, including the elevated serum FGF23 and hypophosphatemic rickets." (PMID 36246908, 2022). "Mutations in four genes, FGF23 itself, PHEX, DMP1 and ENPP1, have been reported to remarkably increase the plasma levels of FGF23, leading to hereditary hypophosphatemic rickets." (PMID 22615579, 2012). "The Dmp1-null mouse model also exhibits hypophosphatemic rickets, which indicates the important role of the DMP1 gene in the development of normal bone formation." (PMID 21747952, 2011). "Our study shows that the 57-kDa fragment recapitulates the function of full-length DMP-1 in regulation of mineralization and osteocyte maturation and highlights the molecular mechanisms responsible for hypophosphatemic rickets." (PMID 20734454, 2011). "Autosomal-recessive forms of hypophosphatemic rickets (ARHR1 and 2) are either caused by pathogenic variants in the dentine matrix acidic phosphoprotein 1 (DMP1) gene or in the ectonucleotide pyrophosphatase/phosphodiesterase 1 (ENPP1) gene, which are both expressed in bone and teeth." (PMID 34910242, 2022). "Osteocytes express FGF23 and other multiple genes responsible for hereditary hypophosphatemic rickets, which include phosphate-regulating gene homologous to endopeptidase on X chromosome (PHEX), dentin matrix protein 1 (DMP1), and family with sequence similarity 20, member C (FAM20C)." (PMID 36246908, 2022). "Anti-FGF23 antibody or gene therapy targeting DMP1, FGF23, or PHEX, could be a future direction to treat hypophosphatemic rickets." (PMID 32733380, 2020). "In addition, some molecules responsible for hereditary hypophosphatemic rickets, such as PHEX and DMP1, are also highly expressed in osteocytes." (PMID 24710520, 2014).
breast carcinoma (7 papers, 2009 to 2024). "The bioinformatic analysis of our dataset also unveiled a new cell population descended from Dmp1+ cells characterized by high expression of genes associated with cancer-associated fibroblasts and increased in bones colonized by breast cancer cells." (PMID 38558984, 2024). "Cyclin D-binding Myb-like Protein 1 (DMP1) is a critical tumor suppressor gene in breast cancer, and DMP1 splicing results in splice variants DMP1α, DMP1β and DMP1γ." (PMID 30463359, 2018). "Our data demonstrate critical roles of Dmp1 in preventing mammary tumorigenesis and raise the possibility of treating breast cancer by restoring Dmp1α expression." (PMID 24205004, 2013). "These transgenic mice will be useful to predict tumor-suppressive effects of Dmp1 in other transgenic mice that are prone to mammary tumor development, and identify novel Dmp1 target genes/proteins in vivo." (PMID 24205004, 2013). "Overexpression of cyclin D1, which is found to be overexpressed in 60–80% of breast cancer tumors, inhibits the transcriptional activity of DMP1 and antagonizes its function." (PMID 19671193, 2009).
hyperphosphatemia (7 papers, 2008 to 2023). Abnormally high level of phosphate in the blood. "Considering the marked hypoferremia and hyperphosphatemia observed in the conditional‐null mice, although the Dmp1‐Cre is known to efficiently recombine the flox‐Fgf23 allele, the sum of both of these systemic Fgf23 drivers may override the suppressive abilities of the targeted deletion." (PMID 35656701, 2022). "Despite impaired kidney function and worsened hyperphosphatemia, DMP1 prevented development of LVH and improved Col4a3−/− survival." (PMID 31044094, 2019). "This indicates that DMP1 specifically inhibits FGF23 production and that the inhibitory effects of DMP1 may supersede any direct stimulatory effects of hyperphosphatemia." (PMID 31044094, 2019). "Col4a3−/− mice demonstrated impaired kidney function, reduced bone DMP1 expression, reduced bone mass, altered osteocyte morphology and connectivity, increased osteocyte apoptosis, increased serum FGF23, hyperphosphatemia, left ventricular hypertrophy (LVH), and reduced survival." (PMID 31044094, 2019).
Osteopenia (7 papers, 2012 to 2023). Osteopenia is a term to define bone density that is not normal but also not as low as osteoporosis. "Our group previously reported that osteocyte-specific Kindlin-2 deletion through 10-kb mouse dentin matrix protein 1 (Dmp1-Cre) caused obvious osteopenia in mice, which deteriorates bone accrual and homeostasis and parathyroid hormone bone anabolism." (PMID 33767359, 2021). "Here we report that, with aging, Dmp1-PPRKO mice develop a significant osteopenia characterized by reduced trabecular bone, whereas the cortical compartment is relatively unaffected." (PMID 34968192, 2021). "To delineate the cellular mechanism of the age-related osteopenia in the Dmp1-PPRKO animals, we performed histomorphometric analysis on the L5 and the femora of adult and middle-aged mice." (PMID 34968192, 2021). "Conditional deletion of Pkd1 in osteoblasts using either Osteocalcin(Oc)-Cre or Dmp1-Cre results in defective osteoblast-mediated postnatal bone formation and osteopenia." (PMID 23029375, 2012). "In this regard, the selective deletion of Pkd1 in osteoblasts by using Osteocalcin(Oc)-Cre and in osteocytes by using Dmp1-Cre results in osteopenia in adult mice because of defects in osteoblast-mediated bone formation." (PMID 23029375, 2012). "We investigated whether the osteopenia present in the Dmp1-PPRKO animals at 13 months old was due to increased osteocyte apoptosis." (PMID 34968192, 2021). "Here, we show that deleting Kindlin-2 from osteoblasts using the 2.3-kb mouse Col1a1-Cre transgene minimally impacts bone mass in mice, but deleting Kindlin-2 using the 10-kb mouse Dmp1-Cre transgene, which targets osteocytes and mature osteoblasts, results in striking osteopenia in mice." (PMID 31934494, 2020). "Mice lacking PPR in osteocyte (Dmp1-PPRKO) display an age-dependent osteopenia characterized by a significant decrease in osteoblast activity and increase in osteoclast number and activity." (PMID 34968192, 2021). "Thus, it is unlikely that the lack of osteopenia in the calvariae of cKO mice is due to differences of Kindlin-2 expression and/or Dmp1-Cre activity in osteocytes between the two types of bones." (PMID 33767359, 2021).
chronic kidney disease (6 papers, 2012 to 2021). Impairment of the renal function secondary to chronic kidney damage persisting for three or more months. "Discovering this novel protective role of DMP1 may have clinical relevance in protecting the cells from apoptosis in high-phosphate environments as observed in chronic kidney disease (CKD)." (PMID 22879941, 2012). "Chronic kidney disease reduces DMP1 expression in osteocytes, while DMP1 supplementation prevents osteocyte apoptosis, lowers FGF23 expression, increases serum phosphate, and prevents the development of left ventricular hypertrophy in a chronic kidney disease mice model." (PMID 32733380, 2020).
dentinogenesis imperfecta (5 papers, 2013 to 2025). Dentinogenesis imperfecta (DGI) is a hereditary dentin defect characterized by abnormal dentin structure resulting in abnormal tooth development. "DSPP and DMP1 gene mutations in humans and mice caused dentinogenesis imperfecta (DGI) 5–9." (PMID 37790473, 2023). "BMP2-deficient teeth display morphological features similar to dentinogenesis imperfecta (DGI), which is associated with mutations in the DMP1 and DSPP genes." (PMID 40133254, 2025). "DMP-1, a candidate protein for dentinogenesis imperfecta, is present in the extracellular matrix of dentine and bone." (PMID 25007265, 2014). "More importantly, as the major dentinal non-collagenous proteins, DSPP is essential for dentin mineralization, while DMP-1 is also specific for dentin and is considered as a candidate gene for dentinogenesis imperfecta." (PMID 23675415, 2013). "Teeth lacking Bmp2 exhibit a morphology reminiscent of dentinogenesis imperfecta (DGI), associated with mutations in dentin matrix protein 1 (DMP1) and dentin sialophosphoprotein (DSPP) genes." (PMID 37790473, 2023).
X-linked hypophosphatemic rickets (5 papers, 2012 to 2023). "Mouse studies have suggested that enhanced FGF receptor (FGFR) signaling is involved in the overproduction of FGF23 in PHEX-deficient X-linked hypophosphatemic rickets (XLH) and DMP1-deficient autosomal recessive hypophosphatemic rickets type 1." (PMID 36246908, 2022).
hyperparathyroidism (4 papers, 2008 to 2025). Hyperfunction of the parathyroid glands resulting in the overproduction of parathyroid hormone. "Several skeletal features of the DMP1-caPTHR1 mice are similar to those found in patients with hyperparathyroidism, including a high rate of bone remodeling, increased cancellous bone, and increased cortical porosity." (PMID 18698360, 2008).
osteoporosis (4 papers, 2022 to 2024). A condition of reduced bone mass, with decreased cortical thickness and a decrease in the number and size of the trabeculae of cancellous bone (but normal chemical composition), resulting in increased fracture incidence. "Indeed, partial ablation of the α-subunit of diphtheria toxin in dentin matrix protein 1 (DMP1)-positive osteocytes in a mouse model of conditional osteocyte deletion caused severe osteoporosis and reduced lifespan." (PMID 39335461, 2024). "Other osteocyte-secreted factors have been reported to be elevated in monogenetic osteoporosis and renal osteodystrophy like FGF23 and DMP1." (PMID 39062269, 2024).
osteosarcoma (4 papers, 2012 to 2023). A usually aggressive malignant bone-forming mesenchymal neoplasm, predominantly affecting adolescents and young adults. "Expression of osteocyte markers (i.e., DMP1, MEPE, or PHEX) has been observed in the osteoblastic subtype of human osteosarcoma, indicating that osteocytes may potentially serve as progenitors for osteosarcoma cells." (PMID 37174109, 2023).
periodontitis (4 papers, 2019 to 2024). An acute or chronic inflammatory process that affects the tissues that surround and support the teeth. "There were more TUNEL- and DMP1-positive cells in the periodontitis group than in the control group." (PMID 38670955, 2024). "The periodontitis group exhibited increased TfR1 expression in both the gingiva and alveolar bone and enhanced TfR1 expression was detected in DMP1-positive cells by double immunofluorescence staining, further suggesting that osteogenic cells undergo ferroptosis in periodontitis." (PMID 38670955, 2024). "In contrast, both Rag1−/−; Dmp1-Cre; Myd88fl/fl and Dmp1-Cre;Ranklfl/fl mice exhibited a significant rescue from alveolar bone osteolysis, thereby confirming that osteocytes are the primary source of RANKL in Pg-induced periodontitis." (PMID 36333322, 2022).
dentin dysplasia (3 papers, 2017 to 2023). Dentin dysplasia (DD) is a rare disorder belonging to the group of hereditary dentin defects and is characterized by abnormal dentin structure and root development resulting in abnormal tooth development. "Whole-genome RNA-sequencing analysis of embryonic day (E) 14.5 cap stage molars revealed reductions in early expressed enamel matrix components (Odontogenic ameloblast-associated protein) and dentin dysplasia targets (Dentin matrix acidic phosphoprotein 1)." (PMID 32908163, 2020).
lung carcinoma (3 papers, 2008 to 2025). "Our report suggested the haploid-insufficiency of Dmp1 in lung cancer suppression." (PMID 21892281, 2008).